ATP5MK (ATP synthase membrane subunit k)
Description:
Subunit k, of the mitochondrial membrane ATP synthase complex (F(1)F(0) ATP synthase or Complex V) that produces ATP from ADP in the presence of a proton gradient across the membrane which is generated by electron transport complexes of the respiratory chain (Probable). ATP synthase complex consist of a soluble F(1) head domain - the catalytic core - and a membrane F(1) domain - the membrane proton channel (By similarity). These two domains are linked by a central stalk rotating inside the F(1) region and a stationary peripheral stalk (By similarity). During catalysis, ATP synthesis in the catalytic domain of F(1) is coupled via a rotary mechanism of the central stalk subunits to proton translocation (Probable). In vivo, can only synthesize ATP although its ATP hydrolase activity can be activated artificially in vitro (By similarity). Part of the complex F(0) domain (By similarity). Required for dimerization of the ATP synthase complex and as such regulates ATP synthesis in the mitochondria.
Synonyms: ATP5MD; DAPIT; HCVFTP2; USMG5; MGC14697; bA792D24.4; AGP; MC5DN6
Tractability: Antibody: UniProt predicts a signal peptide or a membrane-spanning region. PROTAC: ubiquitination databases record sites on it.
Gene: Protein-coding gene on chromosome 10 (103,388,991 to 103,396,492, reverse strand). Ensembl gene ENSG00000173915.
Subcellular location: Mitochondrion membrane
Subcellular location (Human Protein Atlas): Mitochondria
Pathways (Reactome):
Metabolism: Formation of ATP by chemiosmotic coupling
Organelle biogenesis and maintenance: Cristae formation
Gene Ontology:
Biological process: proton motive force-driven ATP synthesis
Cellular component: mitochondrial membrane; mitochondrion; proton-transporting ATP synthase complex; mitochondrial inner membrane
Genetic constraint (gnomAD): Loss-of-function variants: 3 observed, 4.47 expected, observed/expected ratio (o/e) 0.67, 90% interval 0.3 to 1.62. That is too few expected variants to judge how well the gene tolerates losing a copy. Missense variants: 46 observed, 55.41 expected, observed/expected ratio (o/e) 0.83, 90% interval 0.65 to 1.06. Synonymous variants: 28 observed, 23.52 expected, observed/expected ratio (o/e) 1.19, 90% interval 0.88 to 1.63.
Gene-disease validity (ClinGen):
ClinGen rates the evidence that ATP5MK causes each of these diseases.
Leigh syndrome (autosomal recessive): Moderate. A progressive neurological disease defined by specific neuropathological features associating brainstem and basal ganglia lesions.
mitochondrial disease (autosomal recessive): Moderate.
Homologues: Orthologues: chimpanzee ATP5MK (100% identical), pig ATP5MK (93% identical), rat Atp5mk (91% identical), dog ATP5MK (90% identical), guinea pig ATP5MK (90% identical), mouse Atp5mk (90% identical), rat Atp5mk-ps2 (90% identical), dog ATP5MK (88% identical).
Diseases named in the same sentence as ATP5MK in open-access papers:
ATP5MK is named in the same sentence as 29 diseases in open-access papers, as found by Europe PMC text mining. Sharing a sentence is not in itself a finding about the gene and the disease. The quoted sentences say what the papers report.
schizophrenia (2 papers, 2021 to 2026). A major psychotic disorder characterized by abnormalities in the perception or expression of reality. "Placentae from ∆9-tetrahydrocannabinol-exposed males and females revealed altered expression of genes previously identified in human transcriptomic datasets of schizophrenia (i.e., Furin, Rccd1, and Atp5mk), with some expression changes being sex-specific (i.e., Eif5, Rps10, Vps33b, and Iqgap1)." (PMID 40827685, 2026).
ATP5MK also shares sentences with these, for which no sentence is quoted: periodontitis (34 papers); periodontal disease (7); diabetes (5); cancer (3); ischemic stroke (3); Stroke (3); aggressive periodontitis (2); chronic periodontitis (2); gingivitis (2); Leigh syndrome (2); Arthritis (1); co-infection (1); colon cancer (1); Coronary Artery Disease (1); cutaneous melanoma (1); heart failure (1); infection (1); ischemia (1); ischemic cardiomyopathy (1); juvenile periodontitis (1); mood disorder (1); multiple mitochondrial dysfunctions syndrome 4 (1); multiple myeloma (1); Nephropathy (1); neuroblastoma (1); neurological disorder (1); type 2 diabetes (1); white matter hyperintensities (1).